PIDD1 (p53-induced death domain protein 1)
Description:
Associated with CRADD and the CASP2 caspase, it forms the PIDDosome a complex that activates CASP2 and triggers apoptosis. Associated with IKBKG and RIPK1, it enhances sumoylation and ubiquitination of IKBKG which is important for activation of the transcription factor NF-kappa-B.
Synonyms: LRDD; PIDD; MGC16925; DKFZp434D229; MRT75; altPIDD1
Tractability: PROTAC: ubiquitination databases record sites on it.
Gene: Protein-coding gene on chromosome 11 (799,179 to 809,753, reverse strand). Ensembl gene ENSG00000177595.
Subcellular location: Cytoplasm; Nucleus; Cytoplasm, cytoskeleton
Subcellular location (Human Protein Atlas): Cytosol; Golgi apparatus
Gene Ontology:
Molecular function: endopeptidase activity; protein binding; death receptor binding
Biological process: apoptotic process; DNA damage response; negative regulation of apoptotic process; protein autoprocessing; regulation of canonical NF-kappaB signal transduction; intracellular signal transduction; positive regulation of apoptotic process; signal transduction
Cellular component: cytoplasm; cytosol; endopeptidase complex; nucleus; nucleolus; nucleoplasm
Genetic constraint (gnomAD): Loss-of-function variants: 74 observed, 72.6 expected, observed/expected ratio (o/e) 1.02, 90% interval 0.84 to 1.24. The synonymous counts are far from expectation, so gnomAD's model fits this gene poorly and the ratio says little. Missense variants: 1,329 observed, 1,173.3 expected, observed/expected ratio (o/e) 1.13, 90% interval 1.08 to 1.18. Synonymous variants: 655 observed, 524.17 expected, observed/expected ratio (o/e) 1.25, 90% interval 1.17 to 1.33.
Gene-disease validity (ClinGen):
ClinGen rates the evidence that PIDD1 causes each of these diseases.
intellectual developmental disorder, autosomal recessive 75, with neuropsychiatric features and variant lissencephaly (autosomal recessive): Definitive.
Homologues: Orthologues: chimpanzee PIDD1 (97% identical), macaque PIDD1 (90% identical), pig PIDD1 (84% identical), dog PIDD1 (83% identical), mouse Pidd1 (81% identical), rat Pidd1 (80% identical), guinea pig PIDD1 (80% identical), tropical clawed frog pidd1 (49% identical). Paralogues in human: SCRIB (17% identical), ERBIN (17% identical), PHLPP2 (16% identical), PHLPP1 (16% identical), MFHAS1 (16% identical), LRRC7 (15% identical), LRRC40 (14% identical), LRRC1 (14% identical), LRRK1 (13% identical), LRRIQ4 (13% identical), SHOC2 (13% identical), LRRD1 (12% identical), and 19 more.
Diseases named in the same sentence as PIDD1 in open-access papers:
PIDD1 is named in the same sentence as 42 diseases in open-access papers, as found by Europe PMC text mining. Sharing a sentence is not in itself a finding about the gene and the disease. The quoted sentences say what the papers report.
Intellectual disability (5 papers, 2021 to 2024). "Recently, we, and others, have reported homozygous PIDD1 mutations segregating in autosomal recessive non-syndromic intellectual disability." (PMID 35052391, 2021). "Biallelic truncating mutations in CRADD—the protein bridging PIDD1 and caspase-2—have been reported in intellectual disability (ID), and in a form of lissencephaly." (PMID 33414379, 2021). "More recently, biallelic pathogenic variants in PIDD1 have been described in a few families with apparently nonsydnromic intellectual disability." (PMID 34163010, 2021).
lymphoma (3 papers, 2015 to 2020). A malignant (clonal) proliferation of B- lymphocytes or T- lymphocytes which involves the lymph nodes, bone marrow and/or extranodal sites. "As loss of Caspase-2 leads to an acceleration of tumor onset in the Eμ-Myc mouse lymphoma model, whereas loss of Pidd1 actually delays onset of this disease, we set out to interrogate the role of Raidd in cancer in more detail." (PMID 25857265, 2015).
developmental delay (2 papers, 2019 to 2021). "It is noteworthy that some of the CNVs reported in ARTN, C2orf82, and PIDD1 are related to brain-specific and overall developmental delay at both fetal and postnatal stages." (PMID 31582733, 2019).
Lissencephaly (2 papers, 2021 to 2024). A spectrum of malformations of cortical development caused by insufficient neuronal migration that subsumes the terms agyria, pachygyria and subcortical band heterotopia. "Examination of MRI from two affected individuals with the PIDD1 Gln863* mutation did show subtle signs of lissencephaly in one (the elder) of the two individuals; however, the images available to us were poor quality." (PMID 33414379, 2021). "Together this indicates that PIDD1 mutations in humans may cause ID (and possibly lissencephaly) either through gain of function or secondarily, due to altered scaffolding properties, while complete loss of PIDD1, as modeled in mice, may be well tolerated or is compensated for." (PMID 33414379, 2021). "Thus, as with CRADD, mutations in PIDD1 may also be associated with lissencephaly." (PMID 33414379, 2021). "This adds weight to lissencephaly being a common feature for both CRADD and PIDD1-related disorders." (PMID 33414379, 2021).
lung adenocarcinoma (2 papers, 2019 to 2021). A carcinoma that arises from the lung and is characterized by the presence of malignant glandular epithelial cells. "To explore the potential consequences of mutation for PIDDosome function we performed reconstitution assays where PIDD1-deficient U2OS osteosarcoma and A549 lung-adenocarcinoma cells were used to transiently express sgRNA resistant WT, mutant, or truncated PIDD1 proteins." (PMID 33414379, 2021).
Anxiety (1 paper, 2021). Intense feelings of nervousness, tension, or panic often arise in response to interpersonal stresses. "Although the phenotypic consequences of Pidd1 knockout in mice did not recapitulate the cognitive deficit seen in the patients with biallelic disruption of the PIDD1 C-terminal DD, there were mild but significant anxiety phenotypes noted." (PMID 33414379, 2021). "Pidd1 null mice show decreased anxiety, but no motor abnormalities." (PMID 33414379, 2021).
B-cell lymphomas (1 paper, 2015). "Strikingly, Raidd deficiency also had no influence on tumor latency in c-Myc-driven B-cell lymphomas, contrasting the findings with Caspase-2- or Pidd1-deficient mice, where Caspase-2 acts as a tumor suppressor and Pidd1 as a tumor promoter in this model." (PMID 25857265, 2015).
cognitive deficit (1 paper, 2021). "Future work will focus on whether Pidd1 mice also share such features, regardless of the lack of a clear cognitive deficit." (PMID 33414379, 2021).
COVID-19 (1 paper, 2021). A disease caused by infection with severe acute respiratory syndrome coronavirus 2. "Two sets of three genes (CMB9-55F22.1, PIDD1, RPLP2), all of which are associated with the predominant lead COVID-19 hg-replicated SNP (rs3934992), constituted top 10% of statistically significant eGenes and sGenes, respectively." (PMID 34027315, 2021). "In terms of immunity, expression changes in CD151, PIDD1, and DPP9—genes involved in immune cell activation and NF-kB-mediated immune response —were associated with two distinct COVID-19 hg-replicated SNPs (rs3934992, rs12610495)." (PMID 34027315, 2021).
depression (1 paper, 2022). "As the hub genes in the PPI networks, the expression of Mpp1 and Pidd1 may provide diagnostic and therapeutic value for depression." (PMID 35771226, 2022). "It is reported that Pidd1 may be participated in depression pathogenesis via Bdnf in the downstream." (PMID 35771226, 2022). "Consequently, further study is needed to understand the underlying mechanism of these DEGs (including Eps8l1, Plcb2, Mpp1, Pidd1) in Asmt-related depression and exercise effects, thus provide new targets for the treatment of exercise for depression." (PMID 35771226, 2022).
glioma (1 paper, 2023). A benign or malignant brain and spinal cord tumor that arises from glial cells (astrocytes, oligodendrocytes, ependymal cells).
hepatocellular carcinoma (1 paper, 2020). A malignant tumor that arises from hepatocytes. "Probing the Provisional Liver Hepatocellular Carcinoma TCGA data set we found that CASP2 and PIDD1 transcript levels are significantly upregulated in human HCC across all disease stages." (PMID 33225610, 2020).
liver cancer (1 paper, 2020). An epithelial or non-epithelial malignant neoplasm that arises from the liver. "We found that CASP2 and PIDD1 expression is increased in human HCC as well as DEN‐induced murine liver cancer." (PMID 33225610, 2020).
megalencephaly (1 paper, 2021). A congenital abnormality in which the occipitofrontal circumference is greater than two standard deviations above the mean for a given age. "First, it must be noticed that megalencephaly is only described in the CRADD-related disorder while it is absent in PIDD1- and other LIS-related disorders." (PMID 34163010, 2021).
Pachygyria (1 paper, 2024). Pachygyria is a malformation of cortical development with abnormally wide gyri with sulci 1,5-3 cm apart and abnormally thick cortex measuring more than 5 mm (radiological definition). "In the past few years, biallelic pathogenic variants in CRADD and PIDD1 have been associated with LIS, anterior-predominant pachygyria, and ID." (PMID 37880421, 2024). "In summary, we present seven patients with CASP2-related DD/ID and all patients for whom brain MRIs were available have anterior-predominant LIS and pachygyria in neuroimaging, similar to previously reported CRADD and PIDD1 patients." (PMID 37880421, 2024). "All patients from whom brain MRIs were available had a typical fronto-temporal LIS and pachygyria, remarkably resembling the CRADD and PIDD1-related neuroimaging findings." (PMID 37880421, 2024).
rheumatoid arthritis (1 paper, 2025). A chronic, systemic autoimmune disorder characterized by inflammation in the synovial membranes and articular surfaces. "For example, investigating PIDD1 in the fetal cortical tissue identified links with eye conditions and rheumatoid arthritis, both previously associated with ADHD." (PMID 40000109, 2025). "PIDD1 was associated with rheumatoid arthritis through the network connecting it with TRAF1." (PMID 40000109, 2025). "Through this network, PIDD1 links indirectly to TRAF1, which, in both whole blood and fetal cortical tissues, is regulated by SNPs associated with rheumatoid arthritis." (PMID 40000109, 2025). "Therefore, the apoptosis network involving PIDD1 may impact ADHD in the brain and rheumatoid arthritis in the liver." (PMID 40000109, 2025).
viral infection (1 paper, 2021). "These potential mechanisms include NF-kB-mediated immune response (i.e. PIDD1), immune synaptic interaction involved in T cell activation (i.e. CD151) and T cell exhaustion in viral infection (i.e. CD244)." (PMID 34027315, 2021).
tumor (12 papers, 2015 to 2024). "In a model of c-Myc-induced lymphomagenesis, loss of caspase-2 accelerated tumor growth, but loss of PIDD1 suppressed tumor formation, suggesting that caspase-2 does not depend on PIDD1 to suppress tumors." (PMID 33425918, 2020). "Taken together, this suggests that the transcriptional upregulation in HCC tumors observed for CASP2 and PIDD1 is directly linked to the higher proliferation rates in the tumor while the expression of RAIDD is uncoupled from the proliferative state." (PMID 33225610, 2020). "The observation that loss of PIDD1 suppressed tumor formation may be due to PIDD1’s known role in activating the pro-survival NFκB pathway in response to genotoxic stress." (PMID 33425918, 2020). "Similar to the results obtained in mice, we found caspase‐2 and PIDD1 protein to be clearly elevated in human tumor tissue compared to matched non‐tumorous liver." (PMID 33225610, 2020). "The up-regulated genes were associated with apoptosis induction (BTG2, TP73 and PIDD1) and cell cycle arrest (RPRM and CDNK1A), consistent with the tumor suppressive function of PKNOX2." (PMID 30745575, 2019). "The same trends were observed for transcript levels of Casp2 and Pidd1 in tumor tissue (Fig EV2A)." (PMID 33225610, 2020). "Overall, these data demonstrate that the adaptor protein Raidd is not limiting Myc-driven tumorigenesis thereby uncoupling the tumor-suppressor function of Caspase-2 from Raidd-dependent autoactivation and the oncogenic potential of Pidd1 from Raidd-modulated NF-κB signaling." (PMID 25857265, 2015). "The role of Caspase-2 as a tumor suppressor and that of Pidd1 as a tumor promoter can therefore be uncoupled from their ability to interact with the Raidd scaffold, pointing toward the existence of alternative signaling modules engaging these two proteins in this context." (PMID 25857265, 2015). "Tumor suppression by caspase-2 has also been reported to be independent of both PIDD1 and RAIDD in certain models." (PMID 33425918, 2020). "The results thus indicate that Caspase-2-mediated tumor suppression is independent of both Pidd1 and Raidd." (PMID 25857265, 2015). "Due to the lack of suitable antibodies, we could not confirm increased PIDD1 protein expression in tumor tissue." (PMID 33225610, 2020).
cancer (7 papers, 2014 to 2023). A tumor composed of atypical neoplastic, often pleomorphic cells that invade other tissues. "As Raidd was reported to have a role in DNA-damage-induced apoptosis because of its ability to form a complex with Pidd1 and Caspase-2,19 we used different cancer models to evaluate the impact of Raidd in tumorigenesis induced by DNA lesions." (PMID 25857265, 2015). "Of note, PIDD1 and CRADD have been reported to activate caspase-2 in various cellular contexts, including DNA damage or centrosome amplification in cancer cells as well as amyloid-induced neuronal toxicity." (PMID 33414379, 2021). "Overlap of essential E‐boxes for four cancer cell lines revealed only three (1%) common E‐boxes: chr1_BS1363_CACAATG with neighbor genes MECR and PTPRU, chr11_BS79_CGCGTG localized near RPLP2 and PIDD1, and chr18_BS691_CATGTG adjacent to RBFA and TXNL4A." (PMID 37519063, 2023). "Although METTL3 is reported to promote translation in human cancer cells independent of its catalytic activity and m6A readers, the METTL3 knockdown resulted in a better association of our candidate mRNAs with polysomes, especially PHLDA1, PIDD1 and PMAIP1, under cisplatin treatment conditions." (PMID 36497162, 2022).
neurodevelopmental disorder (4 papers, 2021 to 2024). A behavioral and cognitive disorder with onset during the developmental period that involves impaired or aberrant development of intellectual, motor, or social functions. "Biallelic truncating variants in CASP2 cause similar neurodevelopmental disorder with lissencephaly, suggesting that the PIDD1–RAIDD-caspase-2 axis is crucial for normal gyration of developing human neocortex as well as cognition and behavior." (PMID 38676703, 2024). "Thus, similar to biallelic CRADD and PIDD1 loss of function, we observed a mild to moderate neurodevelopmental disorder associated with biallelic CASP2 variants." (PMID 37880421, 2024). "Interestingly, mutations in RAIDD or PIDD1 that impair caspase-2 activation cause neurodevelopmental disorders with pachygyria and psychiatric features." (PMID 38676703, 2024). "Thus, there is accumulating evidence of a role for PIDD1 in neurodevelopmental disorders spanning multiple diagnoses, and with a variety of inheritance patterns." (PMID 33414379, 2021).
PIDD1 also shares sentences with these, for which no sentence is quoted: keratoconus (3 papers); fibrosarcoma (2); lung carcinoma (2); Alzheimer disease (1); autism (1); autism spectrum disorder (1); autosomal recessive intellectual disability (1); blood cancer (1); breast carcinoma (1); Burkitt lymphoma (1); colorectal cancer (1); epilepsy (1); Fuchs endothelial corneal dystrophy (1); gastric cancer (1); infection (1); melanoma (1); neurodegenerative disease (1); non-small cell lung carcinoma (1); osteosarcoma (1); ovarian carcinoma (1); psychiatric disorder (1); T cell lymphomas (1).